DEPDC5 (DEP domain containing 5, GATOR1 subcomplex subunit)
Diseases named in the same sentence as DEPDC5 in open-access papers (continued):
Sharing a sentence is not in itself a finding about the gene and the disease.
epilepsy (continued). "We assembled a cohort of 73 previously unreported probands with rare variants in DEPDC5, NPRL2, and NPRL3 through international networking with diagnostic epilepsy centers." (PMID 30093711, 2019). "Because somatic variants in GATOR1-encoding genes (>400 in DEPDC5, >80 in NPRL2, and >100 in NPRL3 in the COSMIC database) have been mentioned in various cancers, we examined cancer occurrence in epilepsy probands carrying germline GATOR1 variants." (PMID 30093711, 2019). "In the example, only SCN1A, DEPDC5 and GRIN2A are in the top 10 ‘epilepsy’ gene list both as genes with the most variants and most pathogenic variants." (PMID 31114901, 2019). "Humans with heterozygous loss-of-function DEPDC5 variants exhibit epilepsy with or without developmental cortical malformations such as FCD." (PMID 40996830, 2025). "Additionally, a study involving 20 cases of DEPDC5-related epilepsy phenotypes found that medications such as lamotrigine and sodium valproate achieved favorable therapeutic outcomes in some patients." (PMID 41141423, 2025). "Patients with focal DEPDC5-related epilepsy may benefit from the protective effects of fasting through DEPDC5-mediated amino acid sensing in wild-type neurons." (PMID 40996830, 2025). "However, further work is needed to better understand the role of hypomyelination in DEPDC5-related epilepsy." (PMID 40996830, 2025). "The current mouse model can aid in further elucidating the pathology of Depdc5-related epilepsy." (PMID 40996830, 2025). "The mechanisms of epileptogenesis associated with FCD and hyperactive mTOR signaling remain unclear in DEPDC5-related epilepsy." (PMID 40996830, 2025). "Though DEPDC5 mutations are primarily associated with non-lesional epilepsy, they have been identified in about 20% of individuals with structural brain abnormalities." (PMID 40546503, 2025). "This study demonstrates that postnatal DEPDC5 loss and subsequent mTOR hyperactivation without disruption of cortical migration is sufficient to cause epilepsy." (PMID 40996830, 2025). "Consequently, DEPDC5-related epilepsy encompasses a range of epilepsy syndromes, almost all of which being characterized by focal seizures, with seizure onset in a discrete area of the brain." (PMID 38987251, 2024). "DEPDC5 is a common causative gene in patients with epilepsy and malformation of cortical development (MCD) thus suggesting a core role for PNN in the pathogenesis of this particular inherited type of epilepsy." (PMID 38673819, 2024). "Asymptomatic heterozygotes are common in families with DEPDC5-related epilepsy and penetrance could be as low as 60%74,75." (PMID 38987251, 2024). "For instance, in TSC, DEPDC5 or STRADA related seizure disorders, mTORC1 is hyperactive and mTORC2 activity is often reduced or unchanged, indicating that mTORC1 may be the major driver." (PMID 37963879, 2023). "This novel recessive phenotype differs significantly from the epilepsy (with or without FCD) phenotype previously reported with heterozygous loss-of-function germline DEPDC5 variants." (PMID 36067010, 2023). "DEPDC5 may be a target to treat epilepsy because it negatively regulates amino acid sensing through the signaling pathway involving the mammalian target of rapamycin complex 1 (mTORC1)." (PMID 36733671, 2023). "Depdc5, which was also significantly down-regulated in FFI, encodes a subunit of the TORC1 inhibitor complex GATOR1, involved in amino acid–dependent TORC1 activation, and is associated with epilepsy." (PMID 36192034, 2022). "Notably, 30% of these mice exhibited spontaneous seizure followed by sudden death, a phenomenon closely resembling sudden unexpected death in epilepsy (SUDEP), reported in some individuals with DEPDC5-related epilepsy." (PMID 35163267, 2022). "In a study by the Epi4K and Epilepsy Phenome/Genome Project, approximately 3% of patients with familial non-lesional focal epilepsy had deleterious DEPDC5 variants." (PMID 34632383, 2021).
epilepsy (continued). "DEPDC5 mutations are increasingly recognized as one of the most common genetic causes of epilepsy with or without brain malformation." (PMID 33334860, 2021). "DEPDC5 mutations have been increasingly recognized as a common genetic cause of epilepsy with or without brain malformation." (PMID 33334860, 2021). "In the following years, it became clear that mutations in DEPDC5 are also related with brain malformations, notably with focal cortical dysplasia (FCD), which is a major cause of drug-resistant epilepsy and can be associated with sudden unexpected death in epilepsy (SUDEP)." (PMID 34685669, 2021). "In any event, the lack of seizures observed in both heterozygous mice and rats suggests that DEPDC5 haploinsufficiency per se is not sufficient to cause epilepsy." (PMID 28974734, 2017). "Six out of 61 SUDEP had a rare or novel variant in DEPDC5, including 4 with nonsense variants, which accounted for the higher number of DEPDC5 variants in SUDEP compared to people without epilepsy." (PMID 28775708, 2017). "A recent report describing a somatic “second hit” mutation in DEPDC5 in an individual with focal epilepsy and cortical dysplasia suggests that GATOR1 and TSC-associated epilepsies may share this underlying genetic mechanism." (PMID 28974734, 2017). "Indeed, genetic analyses conducted in SUDEP cases have revealed the presence of potentially dangerous genetic alterations in genes involved in the control of cardiac rhythm (such as KCNQ1) and in genes associated with severe forms of epilepsy (such as SCN1A and DEPDC5)." (PMID 41062843, 2026). "DEPDC5 mutations have also been identified in ASD without epilepsy." (PMID 40704780, 2025). "Variants detected in epilepsy-related genes (DEPDC5, CHD2, SCN8A and IQSEC2) have been reported in patients with SCN1A variants and were considered to contribute to blended phenotypes comprising features of the disorder associated with the epilepsy gene and Dravet syndrome." (PMID 38891831, 2024). "In fact, loss-of-function mutations in GATOR1 genes such as DEPDC5, NPRL2, and NPRL3) have been frequently associated with malformations of cortical development leading to focal, drug-resistant epilepsy with fair risks of sudden unexpected death in epilepsy (SUDEP)." (PMID 36639812, 2023). "DEPDC5 gene (OMIM∗614191) encodes disheveled Egl-10 and pleckstrin (DEP) domain containing protein 5, which forms part of the GTPase-activating protein activity toward RAG complex 1, a repressor of the mammalian target of rapamycin (mTOR) signaling pathway that is closely related to epilepsies." (PMID 32848577, 2020). "Epilepsy genes showing a high number of variants with this analysis included another of the neuronal voltage-gated sodium channel genes, SCN2A, whereas the familial focal epilepsy gene, DEPDC5, was ranked first when considering variants that appear only once in the entire dataset." (PMID 28775708, 2017). "Such a favorable surgery outcome, already described in GATORopathies (DEPDC5‐, NPRL2‐, and NPRL3‐related epilepsy), stands in favor of the presurgical sequencing of GATOR1 genes in subjects with either non‐lesional or FCD‐like imaging patterns." (PMID 37491868, 2023). "A review of 213 previously reported individuals with DEPDC5-related disorder demonstrated that 15.2% of individuals do not have epilepsy, 24.3% have intellectual disability, and 33.8% have brain malformations." (PMID 40206130, 2025). "In a child with refractory epilepsy and intellectual disability, we identified an 181 kb deletion in DEPDC5 (chromosome 22) inherited from a parent with well-controlled epilepsy without intellectual disability." (PMID 37471090, 2023). "Although GATOR1 genes, particularly DEPDC5, have been associated to mesial and lateral temporal lobe epilepsy and more frequently to FCD-associated epilepsy, no information about the genetic profile of the TLE and FCD patients is provided in these studies." (PMID 36639812, 2023).
epilepsy (continued). "It suggests that DEPDC5 and GATOR1 play more prominent role in brain development, which may help explain why epilepsy is the predominant phenotype reported in humans with DEPDC5 mutations." (PMID 28974734, 2017). "We adapted this methodology to create a mouse model of focal DEPDC5-related epilepsy without neuronal migration defects via unilateral stereotactic injection of AAV-Cre-GFP into the motor cerebral cortex of postnatal day zero (P0) or P1 Depdc5-floxed (Depdc5c/c or Depdc5c/–) mouse pups." (PMID 40996830, 2025). "Thus, unlike some other epilepsy models [e.g., Depdc5, Scn8a, DBA-1, etc.], this model exhibits irregular breathing with only rare and brief apneas during seizures." (PMID 41326205, 2025). "The majority of the identified variants were predicted to introduce premature stop codons, suggesting that haploinsufficiency of DEPDC5 may result in different subtypes of epilepsies in the absence of a cortical malformation." (PMID 35163267, 2022). "This could be supported by a recent report that DEPDC5, as a single mTOR gene, is a key contributor to a broad spectrum of lesional and non-lesional epilepsies, with variable but highly consistent phenotypes." (PMID 31875159, 2019). "However, only a subset of patients among families with DEPDC5 mutations develop FCD; other family members appear to present non-lesional epilepsy." (PMID 31780880, 2019). "To conclude, this collaborative study emphasizes that GATOR1 genes of the amino acid–sensing branch of the mTORC1 pathway, especially DEPDC5, are key contributors to a broad spectrum of lesional and nonlesional epilepsies, with variable but highly consistent phenotypes." (PMID 30093711, 2019).
focal epilepsy (45 papers, 2014 to 2025). "In a study involving 479 individuals diagnosed with focal epilepsy, eight unrelated participants were identified as carrying distinct pathogenic or likely pathogenic variants in the DEPDC5 gene." (PMID 40546503, 2025). "In recent years, the GATOR1 complex has been shown to play an important role in the pathogenesis of focal epilepsies, with DEPDC5 exhibiting a higher mutation frequency (approximately 85% of reported cases) than NPRL2 (5%) and NPRL3 (10%)." (PMID 41469379, 2025). "This corresponds to a prevalence rate of approximately 1.67% for DEPDC5-associated focal epilepsy within the study population." (PMID 40546503, 2025). "For instance, DEPDC5 mutations have been associated with various focal epilepsies, including TLE, through dysregulation of the mTOR pathway, which controls neuronal growth and excitability." (PMID 41244607, 2025). "For example, in Case 2, the integrated diagnosis would be focal epilepsy with emerging infantile spasms due to right frontal FCD IIa associated with a pathogenic germline DEPDC5 variant." (PMID 40317795, 2025). "These mutations have also been reported in other focal epilepsies, such as temporal lobe epilepsy, and in disease-free individuals, demonstrating the phenotypic heterogeneity and incomplete penetrance of DEPDC5 mutations." (PMID 38966089, 2024). "Mutations in GATOR1-RagA/B-mTORC1 pathway-related genes (DEPDC5, NPRL2, and NPRL3) have been reported in over 180 families with focal epilepsy, with DEPDC5 mutations being the most common, accounting for 85% of all cases." (PMID 38966089, 2024). "In patient E122, with drug-resistant focal epilepsy, and normal brain MRI, we have identified a novel variant in the DEPDC5 gene, a deletion of the entire coding sequence." (PMID 38328757, 2023). "Rodent models have pointed DEPDC5 loss-of-function mutations as a major cause of focal epilepsy mediated by mTORC1 hyperactivation." (PMID 36639812, 2023). "Familial focal epilepsy with variable foci (FFEVF) is considered one of the most common forms of autosomal dominant epilepsy caused by mutations in the DEP domain containing 5 (DEPDC5), NPR2 like (NPRL2), and NPR3 like (NPRL3)." (PMID 36685832, 2022). "Variants in the DEPDC5 have been proved to be main cause of not only various dominant familial focal epilepsies, but also sporadic focal epilepsies." (PMID 35907814, 2022). "Here we describe a 5-month-old male infant with focal epilepsy, and discuss what role a novel DEPDC5 variant plays in the small family of three." (PMID 35907814, 2022). "In the present study, a novel variant in DEPDC5 was detected in the patient with focal epilepsy and his healthy father." (PMID 35907814, 2022). "For example, the penetrance of DEPDC5 variants with different forms of focal epilepsy was incomplete, varying from 50 to 82%." (PMID 34489640, 2021). "In this study, the DEPDC5 gene variants were null variants (c.562+1G>T, c.2731G>T, c.484-1_c.485delGGT) carried by three patients with focal epilepsy (Patient #10, #46, and #84)." (PMID 34489640, 2021). "Recently, mutations in the DEP domain containing protein 5 gene (DEPDC5) have been identified as a crucial genetic cause of focal epilepsy." (PMID 34309811, 2021). "More recently, DEPDC5 variants have been detected in patients with focal epilepsy associated with malformations of cortical development." (PMID 32140648, 2020). "DEPDC5 mutations were originally reported in familial focal epilepsies, but asymptomatic carriers were common." (PMID 32848577, 2020). "In this cohort, eight DEPDC5 mutations were identified in 12 unrelated families featured by focal epilepsies." (PMID 32848577, 2020). "The finding that DEPDC5 is associated with cases of HME following hereditary focal epilepsy clarifies the evidence that DEPDC5 acts as an inhibitor of mTORC1, and variants in DEPDC5." (PMID 32140648, 2020).
focal epilepsy (continued). "Among the 305 patients with focal epilepsies, eight DEPDC5 mutations were identified in 12 unrelated families (sequencing graph)." (PMID 32848577, 2020). "In the present study, we identified eight DEPDC5 mutations in 12 unrelated families from a cohort of 305 patients affected by focal epilepsy (3.9%), including homozygous mutation in a case with FCD." (PMID 32848577, 2020). "To explore the phenotype spectrum of DEPDC5 variants and the possible mechanisms underlying phenotypical variation, we performed targeted next-generation sequencing in 305 patients with focal epilepsies and 91 patients with generalized epilepsies." (PMID 32848577, 2020). "The presence of loss-of-function mutations in DEPDC5 is the most common cause of familial focal epilepsies." (PMID 31780880, 2019). "DEPDC5 variants have also been found in cases with malformation of cortical development and in one sporadic case with focal epilepsy among a cohort of French-Canadian individuals." (PMID 28082152, 2018). "In particular, we identified a deletion resulting in the loss of more than half of the DEPDC5 gene in a patient affected with partial epilepsy." (PMID 29649218, 2018). "Like familial focal epilepsy with variable foci, DEPDC5 mutations show incomplete penetrance, which has been estimated to range from 52 to 82%." (PMID 29075622, 2017). "Recently, a study has demonstrated that DEPDC5 mutation was involved in focal epilepsy, a neurodegenerative disease." (PMID 25551790, 2014). "We have documented 10 patients with focal epilepsy carrying pathogenetic variants (8/10) or variants of uncertain significance (2/10) in the mTORC1 pathway genes (DEPDC5, NPRL3, and MTOR) who developed central apnea in 100% of their seizures, for a total of 31 seizures with respiratory alterations." (PMID 40971258, 2025). "DEPDC5 mutations often result in various focal epilepsies, and DEPDC5 knockdown zebrafish show spontaneous epileptiform activity, increased susceptibility to drug-induced seizures, general hypoactivity, premature death and overall hyperactivation of mTOR signaling." (PMID 36675042, 2023). "We studied four families with familial focal epilepsy carrying DEPDC5 mutations." (PMID 34239491, 2021). "DEPDC5 mutations have been demonstrated to be the most common cause of familial focal epilepsies." (PMID 32848577, 2020). "This could have value, for example, in the treatment of inherited focal epilepsy, which is caused by mutations in DEPDC5 and tends to be drug-resistant or for by-passing the paradoxical increase in cell growth sometimes observed with rapamycin and its analogs." (PMID 32759652, 2020). "Eight DEPDC5 variants were identified in 12 unrelated families with phenotypic heterogeneity, including eight families with 13 individuals with focal epilepsy with febrile seizures plus/febrile seizures (FEFS + /FS) and a homozygous mutation in a case with FCD." (PMID 32848577, 2020). "We identified a homozygous DEPDC5 mutation (p.Pro1031His) in a case with focal cortical dysplasia and eight heterozygous mutations in 11 families with mild focal epilepsies, including 13 patients in eight families with focal epilepsy with febrile seizures plus/febrile seizures (FEFS + /FS)." (PMID 32848577, 2020). "Together these studies identify DEPDC5 as an important new genetic cause of focal epilepsy." (PMID 28974734, 2017). "Notably, Nprl2 and DEPDC5 are tumor suppressor genes while mutations in DEPDC5 are a leading cause of hereditary focal epilepsies." (PMID 27166823, 2016). "DEPDC5 gene has been localized to the long arm of chromosome 22, 22q12.3 and it encodes a cytoplasmic protein which has been recently shown to have a central role in focal epilepsy, a neurological disorder." (PMID 25551790, 2014). "However, a subsequent study showed that DEPDC5 variants may also be associated with lesional focal epilepsy." (PMID 35163267, 2022).